COMT (catechol-O-methyltransferase)
Diseases named in the same sentence as COMT in open-access papers (continued):
Sharing a sentence is not in itself a finding about the gene and the disease.
leukemia (1 paper, 2022). A malignant (clonal) hematologic disorder, involving hematopoietic stem cells and characterized by the presence of primitive or atypical myeloid or lymphoid cells in the bone marrow and the blood. "On the other hand, there were two genes in which overexpression was determined in leukemia-derived cell lines but was not confirmed in patients: COMT and P3H4." (PMID 36428851, 2022).
Lewy body dementia (1 paper, 2022). A progressive form of dementia characterized by the presence of protein deposits called Lewy bodies in the midbrain and cerebral cortex, and loss of cholinergic and dopaminergic neurons. "In accordance, COMT Val158Met polymorphism was not related to psychotic manifestations in Lewy body dementias in another study, suggesting that COMT gene polymorphisms might not significantly affect PDP risk." (PMID 35741861, 2022).
liver fibrosis (1 paper, 2025). "First, we performed an in vitro experiment using the hepatic stellate cell (HSC) line LX-2 cells to evaluate the association between COMT activity and liver fibrosis." (PMID 40715617, 2025).
lumbar disc degeneration (1 paper, 2012). "This study reports an association between variation in the pain gene COMT and reduction in pain in patients with LBP and lumbar disc degeneration at long term follow-up." (PMID 22612913, 2012).
manic episodes (1 paper, 2013). "The aim of this study was to investigate genetic associations between cognitive manic symptoms during manic episodes in bipolar 1 disorder and SNPs in the COMT and DAOA genes." (PMID 23861766, 2013). "Bipolar 1 disorder patients assessed during depressive and manic episodes showed the methionine (Met) allele of COMT to be related to lower test scores compared to healthy controls." (PMID 23861766, 2013).
metastatic cancer (1 paper, 2007). A carcinoma which has spread from the original site of growth to another anatomic site. "In turn, the MRVA itself may be predicted by a single nucleotide polymorphism within COMT, which is also implicated in metastatic cancer." (PMID 18159252, 2007).
methamphetamine dependence (1 paper, 2022). A drug dependence that is a psychological dependency on the regular use of methamphetamine. "It is worth noting that in two of these studies, the genotype effect of COMT Val158Met was only significant in interaction with other risk factors, namely cardiometabolic risk and methamphetamine dependence, neither of which were assessed in the current study." (PMID 35746967, 2022).
neuropathy (1 paper, 2012). A disorder affecting the nervous system that manifests with pain, tingling, numbness, and/or muscle weakness. "We found statistically significant associations of four SNP markers (rs4646316, rs4380755, rs5008499, and rs6591256) in or near COMT, TPMT, and GSTP1 with neuropathy and five SNP markers (rs3788306, rs12189790, rs17420046, rs6938294, and rs6912842) with ototoxicity at the nominal p-value of 0.05." (PMID 23248619, 2012).
open-angle glaucoma (1 paper, 2013). Chronic outflow obstruction of the eye's drainage canals that can lead to increased internal eye pressure and optic nerve damage. "Although no other group has reported on associations between COMT variants and open angle glaucoma, we saw some evidence of internal replication within our data sets." (PMID 23869166, 2013).
oral cancer (1 paper, 2021). "Compared to healthy controls, patients with risk polymorphisms of MAOA, MAOB, and COMT had a significantly enhanced risk of oral cancer." (PMID 34209963, 2021). "A similarly significant pattern was confirmed in the distribution of candidate genotypes of MAOA, MAOB, and COMT among men with oral cancer (n = 209), pharyngeal cancer (n = 88), and OPMD (n = 40), and controls (n = 193)." (PMID 34209963, 2021). "To confirm the differences in the distribution of MAOA, MAOB, and COMT among male patients with oral cancer (n = 209), pharyngeal cancer (n = 88), OPMD (n = 40), and control (n = 193), we divided the patients into four groups." (PMID 34209963, 2021). "In addition, in oral cancer cell lines (OECM-1 and HSC-3), downregulation of COMT mRNA and protein was found to be statistically significant after arecoline treatment (p < 0.05) compared to the control group." (PMID 34209963, 2021).
Ovarian Insufficiency (1 paper, 2014). "So, the aim of this study was to determine whether the Val/Met genetic variation in the steroid hormone metabolism gene COMT is associated with Premature Ovarian Insufficiency in Brazilian women." (PMID 24808926, 2014). "The COMT gene constitutes a crucial element in estrogen metabolism and is assumed to be involved in the development of Premature Ovarian Insufficiency (POI)." (PMID 24808926, 2014).
perinatal depression (1 paper, 2015). "Finally, two further genes implicated in monoaminergic pathways, namely catechol-O-methyltransferase (COMT) and monoamine oxidase A (MAO-A) have also been associated with perinatal depression during stress exposure." (PMID 27617302, 2015).
pharyngeal cancers (1 paper, 2021). "In terms of MAOA, MAOB, and COMT, subjects with the MAOA rs6323 G-allele, MAOB rs6324 G-allele, and COMT rs4633 C/C-genotype had a significantly increased risk of oral and pharyngeal cancers (AOR = 56.99; 95% CI, 15.82–205.31)." (PMID 34209963, 2021). "In terms of MAOB and COMT, subjects with MAOB rs6324 (G-allele) and COMT rs4633 (C/C genotype) had a significantly increased risk of oral and pharyngeal cancers (AOR = 39.27; 95% CI, 15.66–98.47)." (PMID 34209963, 2021). "In terms of MAOA and COMT, subjects with MAOA rs6323 (G-allele) and COMT rs4633 (C/C genotype) had a significantly increased risk of oral and pharyngeal cancers (AOR = 2.94; 95% CI, 1.50–5.76) and risk of OPMD (AOR = 4.74; 95% CI, 1.54–214.57)." (PMID 34209963, 2021). "Subjects with MAOA rs1137070 (T-allele) and COMT rs4633 (C/C genotype) had a significantly increased risk of oral and pharyngeal cancers (AOR = 3.57; 95% CI, 1.86–6.82) and risk of OPMD (AOR = 5.31; 95% CI, 1.76–16.00)." (PMID 34209963, 2021). "Subjects with the MAOA rs1137070 T-allele, MAOB rs6324 G-allele, and COMT rs4633 C/C-genotype had a significantly increased risk of oral and pharyngeal cancers (AOR = 78.62; 95% CI, 20.37–303.45)." (PMID 34209963, 2021). "Carriers of the MAOA rs6323 G-allele, MAOB rs6324 G-allele, and COMT rs4633 C/C-genotype had a prominently increased risk of oral cavity and pharynx cancers (AOR = 56.99; p < 0.001)." (PMID 34209963, 2021). "There were non-significant or lower synergistic effects for smokers combined with the susceptibility SNPs of MAO/COMT on most of the OR ratios between oral and pharyngeal cancers and OPMD." (PMID 34209963, 2021). "Our findings highlight the association of MAO and COMT biomarkers to risks of oral and pharyngeal cancers and OPMD." (PMID 34209963, 2021). "Compared to the healthy control group with rs9605030 C/C+C/T, BQ chewers with the COMT (rs9605030) risk T/T genotype had a significantly synergistic risk of oral and pharyngeal cancers (AOR = 31.57; 95% CI, 6.10–163.34) and risk of OPMD (AOR = 32.29, 95% CI = 3.28–317.97)." (PMID 34209963, 2021). "We assume that three biomarker (MAOA, MAOB, and COMT) variants may contribute to oral and pharyngeal cancers occurrence and may be implicated in the induction of arecoline." (PMID 34209963, 2021). "Compared to the healthy control group (COMT (rs9606186) C/C+G/C genotype), BQ chewers with the COMT rs9606186) risk G/G was significantly related to the risks of oral cavity and pharynx cancers (AOR = 22.13, 95% CI = 10.23–47.84), and the risk of OPMD (AOR = 20.73, 95% CI = 4.97–86.52)." (PMID 34209963, 2021). "The specific aim of this study was to examine the hypothesis that MAO and COMT variants are responsible for oral and pharyngeal cancers and OPMD risks in men." (PMID 34209963, 2021). "MAOA/COMT were implied to have roles in the susceptibility of oral and pharyngeal cancers." (PMID 34209963, 2021). "Therefore, this study was conducted to discover whether MAO and COMT variants contribute a potential role in the risk assessment of oral and pharyngeal cancers and OPMD, particularly among BQ chewers." (PMID 34209963, 2021). "IHC analysis of oral and pharyngeal cancer cases indicated that COMT expression was significantly decreased in cancerous tissues compared to that in non-cancerous tissues (n = 12; p = 0.007)." (PMID 34209963, 2021). "In personalized preventive medicine for oral and pharyngeal cancers, our findings are the first to demonstrate the potential role of lower MAO and COMT expression levels, with the risk polymorphisms utilized as clinical biomarkers." (PMID 34209963, 2021). "This study was conducted to discover whether monoamine oxidase (MAO) and catechol-O-methyltransferase (COMT) variants play a potential role in the risk assessment of oral cavity and pharynx cancers and OPMD, particularly among BQ users." (PMID 34209963, 2021).
pharyngeal cancers (continued). "Although these reports focused on the respective cancers, there is little to no research on the relationship between COMT gene polymorphisms and oral and pharyngeal cancer risk, particularly in OPMD." (PMID 34209963, 2021). "Since arecoline plays a role in the inhibition of MAOA and is responsible for BQ dependence, we speculate that MAO and COMT may be involved in the development of oral and pharyngeal cancers." (PMID 34209963, 2021). "In our findings, the expression of COMT was significantly downregulated in oral and pharyngeal cancer tissues compared to non-cancerous tissue." (PMID 34209963, 2021). "Regarding the occurrence of oral cavity and pharynx cancers and oral potentially malignant disorders (OPMD), no report has ascertained how betel quid (BQ) can induce the expression of monoamine oxidase (MAO) and catechol-O-methyltransferase (COMT)." (PMID 34209963, 2021).
pharyngeal tumor (1 paper, 2021). "In BQ chewers, COMT mRNA expression was significantly lower in pharyngeal tumor tissues than in oral cancerous tissues (p = 0.001)." (PMID 34209963, 2021).
polycystic ovary syndrome (1 paper, 2014). A disorder that manifests as multiple cysts on the ovaries. "In PCOS (Polycystic Ovary Syndrome), catechol O-methyltransferase overexpression and increased levels of 2-ME2 in ovarian granulosa cells represent a mechanism leading to abnormalities of steroidogenesis, follicular arrest, and anovulation." (PMID 24808926, 2014).
psoriasis vulgaris (1 paper, 2009). Plaque psoriasis is the most common presentation of psoriasis. "Based on this concept, we genotyped the COMT-158 A > G polymorphism in an ongoing hospital-based case-control study of psoriasis vulgaris in a Han Chinese population." (PMID 21637643, 2009). "We hypothesized that the COMT-158G > A polymorphism was associated with the risk of psoriasis vulgaris in Han Chinese people." (PMID 21637643, 2009). "To consider the single nucleotide polymorphism in codon 158 (G > A) of the COMT gene, which leads to a valine-methionine substitution resulting in the difference in COMT activity, we analyzed the association between combined genotypes (GG, GA+AA) and the risk of psoriasis vulgaris." (PMID 21637643, 2009). "Our study included only statistical research, not functional investigation of the association between the COMT polymorphism and psoriasis vulgaris, so this hypothesis needs to be tested by further functional studies." (PMID 21637643, 2009). "This suggests that the COMT-158 G > A polymorphism may not contribute to the etiology of psoriasis vulgaris in the Han Chinese population." (PMID 21637643, 2009).
pulmonary disease (1 paper, 2024). "rs4680 COMT polymorphism showed significant effect for successful smoking cessation in patients with pulmonary disease." (PMID 39187813, 2024).
renal cell cancer (1 paper, 2015). "The COMT polymorphism was reported to be associated with renal cell cancer." (PMID 26283601, 2015).
respiratory depression (1 paper, 2025). A decrease in ventilation secondary to impaired signals from the central nervous system. "Although the COMT genotype alone is not a determinant of respiratory depression, its effect on required opioid dose is clinically relevant, as any polymorphism that drives up opioid dosing will magnify respiratory risk in SDB patients." (PMID 40649133, 2025).
rheumatoid arthritis (1 paper, 2023). A chronic, systemic autoimmune disorder characterized by inflammation in the synovial membranes and articular surfaces. "We aimed in this study to investigate the frequency of COMT Val 158 Met polymorphism among patients with FM, rheumatoid arthritis, and in healthy individuals." (PMID 37305098, 2023).
Sepsis (1 paper, 2024). Sepsis is defined as life-threatening organ dysfunction caused by a dysregulated host response to infection. "In patients died from sepsis, the expression levels of COMT and PTGS2 were significantly elevated, PPARA and PPARG were significantly decreased." (PMID 38641695, 2024). "So, we hypothesized that PBA may induce a series of beneficial metabolic changes through the regulation of the immune microenvironment of sepsis by PTGS2, COMT and PPARA." (PMID 38641695, 2024).
sickle cell disease (1 paper, 2022). Sickle cell anemias are chronic hemolytic diseases that may induce three types of acute accidents: severe anemia, severe bacterial infections, and ischemic vasoocclusive accidents (VOA) caused by sickle-shaped red blood cells obstructing small blood vessels and capillaries. "Carriers of the risk allele (G) at COMT rs6269 had greater pain than the protective allele (A) carriers in IBS participants of our study, consistent with the previous study in patients with sickle cell disease." (PMID 35207633, 2022).
spina bifida (1 paper, 2022). A congenital neural tube defect in which vertebrae are not fully formed. "As in the exome dataset of proband SB1A with the EFNB1 variant (rs772228172), four variants were annotated as homozygous (CUBN, COMT, PTCH1 and TRDMT1) and eight variants as heterozygous (CUBN,MTRR, and VANGL1) in the reported spina bifida-related genes." (PMID 35741713, 2022).
tauopathy (1 paper, 2023). Neurodegenerative disorders involving deposition of abnormal tau protein isoforms (tau proteins) in neurons and glial cells in the brain. "We have developed a preclinical tau model of psychotic AD, expressing the P301L human mutant tau gene associated with human tauopathy, together with the deletion of the catechol-o-methyltransferase gene (COMT), in order to drive dopamine neurotransmission." (PMID 37626588, 2023).
type 1 hyperprolinemia (1 paper, 2008). "In a mouse model of type 1 hyperprolinemia, disruption of glutamatergic transmission was observed together with altered cortical dopamine transmission and increased catechol-o-methyltransferase gene expression." (PMID 18989458, 2008).
Urinary incontinence (1 paper, 2024). Loss of the ability to control the urinary bladder leading to involuntary urination. "However, in our study, the use of quercetin did not benefit the case AU, who had slow genotypes in CYP1A1 rs1048943-TT, COMT rs4680 -AA, rs4633-TT and MAO rs6323-TT, and urinary incontinence was observed after quercetin use." (PMID 39148948, 2024).
vitamin B12 deficiency (1 paper, 2023). A disease characterized by low serum levels of vitamin B12, either inherited or acquired. "However, COMT inhibitors can exacerbate vitamin B12 deficiency in patients with PD on L-dopa." (PMID 36839259, 2023).
ZIKV infection (1 paper, 2020). "Here we demonstrate ZIKV-mediated COMT reduction in Vero cells, providing first evidence for a potential molecular link between ZIKV infection and developmental impairment of cells within the auditory and vestibular sensory apparatus of the organ of Corti." (PMID 32850779, 2020).
Zinc deficiency (1 paper, 2025). A deficiency of the essential metal Zinc; an essential cofactor for many enzymes. "In this study, zinc deficiency markedly suppressed the expression of DEGs belonging to CCR, CAD, and COMT gene families." (PMID 40906163, 2025).
cancer (94 papers, 2002 to 2025). A tumor composed of atypical neoplastic, often pleomorphic cells that invade other tissues. "Other genetic variants identified included those within COMT, DNA repair genes, oxidative stress genes, and genes associated with cancer phenotypes." (PMID 41228315, 2025). "This variant, leading to a low activity form of COMT, has been widely studied regarding its association with cancer." (PMID 38337709, 2024). "In terms of the COMT expression, it was significantly associated with immune infiltration in 19 cancers, 13 of which were positively associated and 6 of which were negatively associated." (PMID 37564635, 2023). "In 2 large randomized controlled trials of vitamin E (alpha-tocopherol) supplementation in populations of European ancestry, polymorphisms in the catechol-O-methyltransferase (COMT) gene significantly modified the effect of vitamin E on total cancer incidence." (PMID 37974041, 2023). "Variants of catechol-O-methyltransferase (COMT) were correlated with differential risks of developing chemobrain in cancer survivors." (PMID 35418856, 2022). "Further studies are needed to dissect the potential ROS pathway between MAO and COMT and the possible molecular mechanisms implicated in the development of cancers of the oral cavity and pharynx." (PMID 34209963, 2021). "Genetic polymorphism of human COMT has been associated with increased cancer risk for estrogen-induced cancers owing to decreased COMT activity and inactivation of estrogen metabolites, although this is limited to specific ethnic groups or populations." (PMID 33916785, 2021). "Further markers include thiopurine S-methyltransferase (TPMT) and catechol O-methyltransferase (COMT) variants associated with cisplatin-related hearing damage in frontline paediatric cancer treatment." (PMID 34192550, 2021). "Two large, randomized studies of alpha-tocopherol supplementation showed a reduction in total cancer rates and in BC onset, particularly associated to a specific genotype of the catechol-O-methyltransferase (COMT) gene." (PMID 34869002, 2021). "The presence of the MET158 allele of the COMT gene reduces COMT enzyme activity and was previously reported both to predispose to psychiatric conditions and to be possibly implicated in cancer risk modulation." (PMID 33868590, 2021). "Supporting evidence for the involvement of neurotransmitters comes from studies correlating variants of catechol‐O‐methyltransferase (COMT) with differential risks of developing chemobrain in cancer survivors." (PMID 32346964, 2020). "Here, we studied the association between these three COMT polymorphisms and cisplatin-induced nephrotoxicity in a large cohort of cancer patients in order to assess the clinical relevance of these SNPs and their potential use as predictor in this context." (PMID 32230800, 2020). "Focusing on investigations into the role of COMT rs4680 polymorphism in cancer pain, the G/G genotype was shown to require higher morphine daily doses as compared to G/A and A/A ones." (PMID 30704436, 2019). "This is the first paediatric study addressing the role of COMT polymorphism rs4680 in opioid treatment of cancer patients as well as the inter-individual differences in the response to opioid analgesic therapy." (PMID 30704436, 2019). "The objective of this study was to determine the possible association of variations in the OPRM1, OPRK1 and COMT genes with morphine dosing for opioid therapy in Tunisians cancer patients." (PMID 29259946, 2017). "Many studies have established that the hypermethylation of CpG islands in COMT's promoter is linked to hypoexpression of the gene in some cancers." (PMID 26798414, 2016). "Genetic association studies of cancer-related pain have focused on opioid receptors, COMT enzyme and cytokines." (PMID 26872611, 2016).